SMOX (spermine oxidase)
Diseases named in the same sentence as SMOX in open-access papers (continued):
Sharing a sentence is not in itself a finding about the gene and the disease.
cancer (33 papers, 2017 to 2025). A tumor composed of atypical neoplastic, often pleomorphic cells that invade other tissues. "Dysregulation of SMOX and activated Spm catabolism are associated with inflammation-mediated development of cancer." (PMID 30006473, 2018). "Observational studies have reported SMOX as a source of reactive oxygen species associated with cancer, implying that inhibition of SMOX could be a target for chemoprevention." (PMID 34465810, 2021). "Therefore, the increase in the spermine oxidase enzyme level has been associated with cancer." (PMID 36419080, 2022). "We conducted a comprehensive pan-cancer analysis of SMOX and SUCLG2, to explore their potential roles and mechanisms of action." (PMID 40699864, 2025). "In blood (GSE10715 and GSE174032) and tissue (GSE39582 and GSE44076) samples, relative to the normal groups, the expression of SMOX increased while that of SUCLG2 decreased in the cancer groups." (PMID 40699864, 2025). "In the future, we aim to further investigate the molecular mechanisms of SMOX and SUCLG2 in cancer and potentially offer new diagnostic and treatment approaches for cancers." (PMID 40699864, 2025). "Herein we analyzed SMOX and SUCLG2 expression trends in pan-cancer and explored the association of SMOX and SUCLG2 with cancer prognosis, immunity, cancer cell characteristics, and drug sensitivity." (PMID 40699864, 2025). "In this study, SMOX and SUCLG2 were differentially expressed in pan-cancer tissues and associated with cancer prognosis." (PMID 40699864, 2025). "Polyamines play a key role in inflammation-induced carcinogenesis, but the role of SMOX seems to vary depending on the specific cancer." (PMID 40699864, 2025). "To summarize, our pan-cancer analysis of SMOX and SUCLG2 demonstrated their close association with clinical characteristics, prognosis, cancer immunity, cancer cell characteristics, and drug sensitivity in various cancers." (PMID 40699864, 2025). "Similar outcomes were observed in TCGA dataset, where SMOX expression increased while SUCLG2 expression decreased in cancer tissues." (PMID 40699864, 2025). "Survival analysis in pan-cancer revealed that SMOX and SUCLG2 acted as independent prognostic factors in multiple cancers, and high SMOX expression or low SUCLG2 expression was associated with worse prognosis." (PMID 40699864, 2025). "Our results indicate an association between SMOX, SUCLG2, MSI, and TMB in various cancers, suggesting the potential of SMOX and SUCLG2 as immunotherapy predictors." (PMID 40699864, 2025). "Other cancer-reporting molecules are colibactin, a genotoxin produced by polyketide synthetase-positive Escherichia coli strains, and spermine oxidase (SMO)." (PMID 38674014, 2024). "In response to inflammation and infection, which are associated with increased risk of cancer, expression and activity of the polyamine catabolic enzymes SSAT and SMOX are induced." (PMID 39125742, 2024). "The study also revealed that the oncogene MYC regulates the transcription of key enzymes involved in polyamine metabolism, including ornithine decarboxylase, spermidine synthase, and spermine oxidase in this type of cancer." (PMID 38187259, 2024). "Polyamine blocking therapy (PBT), particularly, blocking ODC1 or SMOX activity, has shown promising therapeutic potentials in several types of cancer." (PMID 37653021, 2023). "In accordance with previous studies indicating that SMOX induction parallels DNA damage in a variety of cancer cell types, here we have also shown that forced SMOX expression is accompanied by the appearance of DNA damage markers in FN-RMS cells." (PMID 36755974, 2023). "SMAB10 staining appeared more frequent in cancer tissues as compared to normal tissues, in line with a possible role of SMOX in cancer development." (PMID 35452470, 2022). "SMOX plays a significant role in driving key oncogenic processes, and its expression is high in certain types of cancers." (PMID 36353478, 2022).
cancer (continued). "In this study, we investigated the important cancer phenotypic role of SMOX expression in CRC cell lines." (PMID 35327428, 2022). "Spermine oxidase plays a crucial role in polyamine catabolism and homeostasis and has come into view as a potential drug target in the field of cancer prevention and interception, among others." (PMID 35452470, 2022). "Immunohistochemistry analysis with the antibody SMAB10 in normal and transformed tissues confirms that SMOX is upregulated in several different cancers." (PMID 35452470, 2022). "AMD1 and SMOX are highly expressed in cancer, which is related to poor prognosis of patients and plays a carcinogenic role." (PMID 36505496, 2022). "Increased understanding of the potential role of polyamines and SMOX is warranted, given the prior studies implicating SMOX in gastric inflammation and cancer and in human IBD." (PMID 29922289, 2018). "No significant changes were noted in polyamine oxidase (PAOX) and spermine oxidase (SMOX) expression between normal and cancer." (PMID 29240775, 2017). "Our data provide insights into the role of SMOX and SUCLG2 in pan-cancer, highlighting their association with prognosis, cancer immunity, and other cancer characteristics and also revealing their significance in cancer progression." (PMID 40699864, 2025). "Expression patterns and underlying mechanisms of metabolism-related genes SMOX and SUCLG2 in pan-cancer remain unclear." (PMID 40699864, 2025). "The expression of SMOX was upregulated in most cancers, except KICH." (PMID 40699864, 2025). "Thus, our data indicate that SMOX activity affects the progression from gastric dysplasia to cancer and implicates acrolein in gastric carcinogenesis by enhancing DNA damage." (PMID 39523394, 2025). "SMOX and SUCLG2 were found to be strongly associated with pan-cancer immunophenotypes (p < 0.001)." (PMID 40699864, 2025). "These suggest that SMOX is a plausible drug target for cancer therapy." (PMID 38617002, 2024). "These two AOs are important pharmacological targets: VAP-1 is involved in various inflammatory diseases and some types of cancer, and SMOX is involved in both the catabolism of polyamines (spermine and spermidine) and in the progression of some types of cancer." (PMID 37687158, 2023). "In contrast, spermine oxidase (SMOX) is more active in cancer HepG2 cells than in normal cells." (PMID 35744995, 2022). "Finally, SMOX activity and expression levels were measured in blood in this study, compared to cancer tissue cells in the observational studies." (PMID 34465810, 2021). "By using the effect estimate form the SSI-IHPS newborn cohort, we found little evidence that the genetic instrument of SMOX activity, rs1741315, was associated with any of the five non-pediatric cancers evaluated." (PMID 34465810, 2021). "Our results do not indicate that genetically driven variation in SMOX activity plays a major role in cancer risk." (PMID 34465810, 2021). "Thus, APAO and SMOX sometimes play opposite roles in determining drug sensitivity of cancer cells." (PMID 30006473, 2018). "Herein, our pan-cancer analysis indicated that SMOX was highly expressed and SUCLG2 was less expressed in most cancers." (PMID 40699864, 2025). "The expression levels of OAZ1, SMOX, SRM, and SMS were significantly elevated in cancer tissues compared to normal tissues, as confirmed by qRT-PCR, Western blot, and immunohistochemistry." (PMID 40823069, 2025). "Both SMOX and SUCLG2 exhibited significant correlations with cancer prognosis, tumor microenvironment, immune infiltration, stemness scores, tumor mutational burden, and microsatellite instability." (PMID 40699864, 2025). "Pathway enrichment analysis involving gene set enrichment analysis revealed that SMOX and SUCLG2 regulate drug metabolism, antigen presentation, and other related pathways, indicating their close relationship with cancer immunity and drug sensitivity." (PMID 40699864, 2025).
cancer (continued). "Our findings revealed a close relationship between SMOX, SUCLG2, clinical characteristics, cancer immunity in CRC." (PMID 40699864, 2025). "ODC1, SAT1, SMOX, and SRM genes are known to decrease cell proliferation in several cancer cell lines." (PMID 31417867, 2019). "SMOX and SUCLG2 play a vital role in cancerogenesis, particularly in cancer metabolism; however, their roles in pan-cancer remain unclear." (PMID 40699864, 2025). "Our findings highlight that SMOX and SUCLG2 are significantly correlated with cancer immunity." (PMID 40699864, 2025). "SMOX and SUCLG2 participate in cancer development and initiation." (PMID 40699864, 2025). "The expression of SMOX was upregulated and that of SUCLG2 was downregulated in most cancers." (PMID 40699864, 2025). "In addition, SMOX activity was the highest in GBM and lowest in LAML, differing from normal tissues in cancers such as COAD, BLCA, and READ." (PMID 40699864, 2025). "Furthermore, we have shown that H. pylori-infected gerbils treated with the SMOX inhibitor MDL 72527 exhibited significantly reduced dysplasia and carcinoma, which was also seen in our genetic ablation of Smox in the FVB/N INS-GAS model." (PMID 39523394, 2025). "Given the importance of the dysregulation of PAs metabolism in cancer, in an attempt to gain insights into the molecular underpinnings of RMS we have investigated the functions of SMOX, a catabolic enzyme regulating SPM oxidation to SPD." (PMID 36755974, 2023). "Furthermore, in cancer cells APAO has been shown to detoxify N-alkylated polyamine analogues, while induction of SMOX is responsible for the toxic effects of N-alkylated polyamine analogues." (PMID 30006473, 2018). "SMOX and SUCLG2 expression levels in 56 pairs of CRC and adjacent normal colorectal tissues were measured by qPCR, which indicated that relative to normal tissues, SMOX was increasingly expressed and SUCLG2 was decreasingly expressed in cancer tissues (p < 0.05)." (PMID 40699864, 2025). "Third, elevated SMOX levels in cancer could also be due to environmental factors not captured by genetics, e.g. short-term pharmacological changes, induced by SMOX inhibitors." (PMID 34465810, 2021). "Interestingly, we reported that deletion of Smox in C57BL6 mice and in cancer-prone transgenic FVB/N mice overexpressing the human gastrin gene reduces the development of gastritis and gastric carcinoma, respectively, demonstrating that SMOX activity mediates H. pylori pathogenesis." (PMID 41282235, 2025). "In this manner, a negative correlation was observed between SMOX and SUCLG2 expression in pan-cancer, consistent with gene expression patterns." (PMID 40699864, 2025). "Accordingly, we have shown that SMOX overexpression further enhances the DNA-PKCs and ATM phosphorylation/activation status induced by IR in FN-RMS cells 3 h post-irradiation, a time interval commonly known to be sufficient for DNA repair in normal but not in cancer cells." (PMID 36755974, 2023).
tumor (25 papers, 2011 to 2026). "Real-time quantitative PCR results disclosed that MPC1, ZG16, RBM47, CPM and DNASE1L3 were expressed at higher levels in adjacent normal tissues than in tumor tissues, and SMOX expression was higher in tumor tissues than in non-tumor tissues." (PMID 38914961, 2024). "They found a significant increase in the expression of polyamine-related genes ODC1, SRM, SMS, SAT1, and spermine oxidase in tumour-affected tissues." (PMID 39408925, 2024). "Western blot results similarly indicated that the expression levels of ODC1 and SMOX proteins in tumor tissues following L.p CMU-Pb-L5 intervention were significantly decreased compared with control group (P < 0.01)." (PMID 39439459, 2024). "The overexpression of SMOX in tumor tissues has been identified as an independent prognostic factor, leading to a poorer overall survival rate." (PMID 38617002, 2024). "Several studies denoted that the SMOX was overexpressed and accelerated tumor growth in HCC or NSCLC patients." (PMID 36339715, 2022). "SMOX overexpression in tumor tissues was an independent prognostic factor, worsening overall survival (p = 0.001)." (PMID 35327428, 2022). "The expression of SMOX in the tumor tissue was assessed by quantitative real-time PCR at the same time points as the expression of SMOX protein by Western blotting." (PMID 36353478, 2022). "Mechanistically, the tumor suppressor miR-124 negatively regulates SMOX expression by binding 3′UTR of SMOX mRNA." (PMID 34068137, 2021). "SMOX, a spermine oxidase, may influence tumour progression through the modulation of polyamine metabolism." (PMID 39915814, 2025). "Elevated levels of SMOX could, therefore, contribute to increased oxidative stress and altered cellular homeostasis, potentially promoting tumour growth and invasiveness." (PMID 39915814, 2025). "Additionally, semi-quantitative analysis of positive cells in the tumor tissues revealed that the expression of SMOX and ODC1 in CMU-Pb-L5 group and 5-Fu group was significantly lower than that in control group (P < 0.001)." (PMID 39439459, 2024). "Under a translational point of view, PA analogues have been developed such as BESpm, BENSpm, and DENSpm have been developed which augment intracellular levels of both SAT1 and SMOX, hence leading to PAs depletion ultimately resulting in tumor-selective cytotoxicity." (PMID 36755974, 2023). "The present study revealed that the active ingredients of YFBP, such as LUT, SIT, MYA, and VAN, might exert anti-tumor effects by downregulating SMOX expression through anti-inflammatory effects and the regulation of the TLR4/NF-κB signaling pathway." (PMID 36353478, 2022). "The results show that luteolin, β-sitosterol, myristic acid, and vanillin may exert anti-tumor effects by downregulating SMOX expression." (PMID 36353478, 2022). "We determined the characteristics of the oral microbiota and its associated metabolic pathways of tumor-bearing mice and proved that tumor-related microorganisms might upregulate the expression of polyamine metabolizing enzyme SMOX in the host cells." (PMID 36046649, 2022). "The active ingredients of YFBP, such as luteolin, β-sitosterol, myristic acid, and vanillin, may exert anti-tumor effects by downregulating SMOX expression via anti-inflammatory signaling and regulation of the TLR4/NF-κB signaling pathway." (PMID 36353478, 2022). "SMOX expression is not linked to poor prognosis, but regional and single-cell transcriptomic reveal that it is highly expressed in the tumour core as well as in peripheral areas where it is mostly expressed by malignant cells." (PMID 39915814, 2025). "This indicates that L.p CMU-Pb-L5 inhibits polyamine synthesis by suppressing SMOX and ODC1 expression, thereby reducing polyamine levels in tumor tissues and inhibiting tumor growth." (PMID 39439459, 2024). "The results demonstrated varying degrees of expression of SMOX and ODC1 in the tumor tissues of all groups." (PMID 39439459, 2024).
tumor (continued). "In this study, we found that the expression levels of SMOX and ODC1 proteins in tumor tissues of mice were significantly decreased after L.p CMU-Pb-L5 intervention." (PMID 39439459, 2024). "Immunohistochemistry was utilized to assess the expression of SMOX and ODC1 in tumor tissues of mice in each group." (PMID 39439459, 2024). "Then, we have examined the relationship between SMOX expression and myogenesis, which is of particular interest in the RMS context being this tumor most likely originated from normal myogenic-derived cells unable to differentiate." (PMID 36755974, 2023). "Consistently, forced expression of SMOX significantly reduces the growth of FN-RMS cells cultured in 3D as spheroids in the presence of serum, an experimental condition which mimics tumor cell proliferation in vivo." (PMID 36755974, 2023). "The cytotoxicity associated with these analogues is partially attributable to significant induction of polyamine catabolism through tumor type-specific induction of spermidine/spermine N1-acetyltransferase (SSAT) and spermine oxidase (SMOX) activity." (PMID 35997336, 2022). "miR-124 has tumor suppressive functions and was reported as a negative regulator of polyamine catabolic enzyme spermine oxidase (SMOX)." (PMID 29675003, 2018). "Immunohistochemistry also showed reduced SMOX and ODC1 protein levels in mouse tumor tissues after L.p CMU-Pb-L5 treatment, consistent with Western blot results, further supporting L.p CMU-Pb-L5's role in inhibiting tumor growth by suppressing polyamine synthesis." (PMID 39439459, 2024). "We show that SMOX inhibition does not affect the proliferation of GIC or iNSC; however, it promotes tumour cell migration, as assessed by wound healing assay, including assessment of gap closure and invasion." (PMID 39915814, 2025).
bacterial infection (12 papers, 2016 to 2025). "SMOX, a member of the polyamine oxidases, catalyzes the oxidative degradation of polyamine spermidine to produce spermidine and is caused by a variety of stimuli, including bacterial infection and oxidative stress." (PMID 34456632, 2021). "SMOX is induced by a variety of stimuli including bacterial infection, polyamine analogues and acetaldehyde exposure." (PMID 29093526, 2017).
neurodegenerative disease (6 papers, 2020 to 2025). A disorder of the central nervous system characterized by gradual and progressive loss of neural tissue and neurologic function. "MDL 72527 is a selective and irreversible inhibitor of polyamine oxidases, particularly spermine oxidase (SMOX), which has shown to have a neuroprotective effect in models of neurodegenerative diseases and ischemic brain injury." (PMID 39915814, 2025). "SMOX-associated dysregulation of polyamine metabolism has been suggested to play a role in neurodegenerative diseases, rendering SMOX a biologically interesting candidate in the pathogenesis of these patients’ disease." (PMID 35087184, 2022). "Our findings suggest that targeting SMOX signaling can be considered a therapeutic strategy to treat neurodegenerative diseases of the eye." (PMID 35216248, 2022). "Emerging evidence suggests that SMOX functions as a common pathological driver across multiple age-related conditions, including neurodegenerative diseases, cardiovascular disorders, and metabolic dysfunctions, all of which share underlying features of chronic oxidative stress and inflammation." (PMID 40563341, 2025). "The involvement of SMOX in neurodegenerative diseases has been reported by other laboratories." (PMID 31991839, 2020). "Interestingly enough, spermine oxidase has roles aging and neurodegenerative diseases." (PMID 34778377, 2021).
adenocarcinoma (3 papers, 2017 to 2024). A common cancer characterized by the presence of malignant glandular cells. "Accordingly, SMOX activity is upregulated in adenocarcinoma cellular model and the use of a demethylating agent can restore miR-124 expression and downregulate SMOX." (PMID 38918813, 2024).
metabolic disorders (1 paper, 2024). "It is known that SMOX can mediate β-alanine metabolism, which is involved in metabolic disorders in offspring exposed to perfluorobutanesulfonic acid during pregnancy." (PMID 38716374, 2024).
SMOX also shares sentences with these, for which no sentence is quoted: cystic fibrosis (21 papers); pneumonia (18); Sepsis (8); bacteremia (5); abscess (4); corneal infection (4); bronchiectasis (3); keratitis (3); respiratory infections (3); brain infarction (2); chronic lung infection (2); colon carcinoma (2); ocular infection (2); prostate intraepithelial neoplasia (2); ventilator-associated pneumonia (2); viral infection (2); acute sinusitis (1); airway hyperresponsiveness (1); alveolitis (1); Autoimmunity (1); bladder cancer (1); breast tumor (1); burn (1); cardiovascular disorder (1); childhood asthma (1); chronic hepatitis (1); co-infections (1); corneal disease (1); COVID-19 (1); E. coli infection (1).
A further 28 diseases each share a sentence with SMOX in 1 paper.